ENDOG (endonuclease G)
Description:
Endonuclease that preferentially catalyzes the cleavage of double-stranded 5-hydroxymethylcytosine (5hmC)-modified DNA. The 5hmC-modified nucleotide does not increase the binding affinity, but instead increases the efficiency of cutting and specifies the site of cleavage for the modified DNAs (By similarity). Shows significantly higher affinity for four-stranded Holliday junction over duplex and single-stranded DNAs (By similarity). Promotes conservative recombination when the DNA is 5hmC-modified. Promotes autophagy through the suppression of mTOR by its phosphorylation-mediated interaction with YWHAG and its endonuclease activity-mediated DNA damage response. GSK3-beta mediated phosphorylation of ENDOG enhances its interaction with YWHAG, leading to the release of TSC2 and PIK3C3 from YWHAG resulting in mTOR pathway suppression and autophagy initiation. Promotes cleavage of mtDNA in response to oxidative and nitrosative stress, in turn inducing compensatory mtDNA replication.
Tractability: PROTAC: ubiquitination databases record sites on it; its protein half-life has been measured.
Target class: Enzyme; Hydrolase
Gene: Protein-coding gene on chromosome 9 (128,818,461 to 128,822,676, forward strand). Ensembl gene ENSG00000167136.
Subcellular location: Mitochondrion
Gene Ontology:
Molecular function: DNA endonuclease activity; protein binding; magnesium ion binding; protein homodimerization activity; RNA endonuclease activity; DNA nuclease activity; hydrolase activity; metal ion binding; nucleic acid binding
Biological process: DNA damage response; mitochondrial DNA catabolic process; negative regulation of TOR signaling; positive regulation of autophagy; positive regulation of mitochondrial DNA replication; apoptotic DNA fragmentation; DNA recombination; cellular response to calcium ion; cellular response to glucose stimulus; cellular response to hypoxia; cellular response to oxidative stress; DNA catabolic process; positive regulation of apoptotic DNA fragmentation; positive regulation of hydrogen peroxide-mediated programmed cell death; response to estradiol; response to mechanical stimulus
Cellular component: mitochondrion; mitochondrial inner membrane; nucleus; perikaryon; perinuclear region of cytoplasm
Genetic constraint (gnomAD): Loss-of-function variants: 22 observed, 16.17 expected, observed/expected ratio (o/e) 1.36, 90% interval 0.97 to 1.85. The upper end of that interval is the gene's LOEUF score, 1.85, which puts it in group 6 of 6, group 1 being the genes least tolerant of losing a copy. Missense variants: 395 observed, 319.62 expected, observed/expected ratio (o/e) 1.24, 90% interval 1.14 to 1.34. Synonymous variants: 168 observed, 139.89 expected, observed/expected ratio (o/e) 1.2, 90% interval 1.06 to 1.37.
Homologues: Orthologues: chimpanzee ENDOG (99% identical), dog ENDOG (94% identical), pig ENDOG (93% identical), guinea pig ENDOG (92% identical), rabbit ENDOG (91% identical), mouse Endog (90% identical), rat Endog (89% identical), zebrafish endog (66% identical), tropical clawed frog endog (65% identical), Drosophila melanogaster EndoG (48% identical), Caenorhabditis elegans cps-6 (38% identical), Drosophila melanogaster Tengl2 (37% identical), and 1 more. Paralogues in human: EXOG (35% identical).
Diseases named in the same sentence as ENDOG in open-access papers:
ENDOG is named in the same sentence as 63 diseases in open-access papers, as found by Europe PMC text mining. Sharing a sentence is not in itself a finding about the gene and the disease. The quoted sentences say what the papers report.
colon cancer (9 papers, 2013 to 2025). "Expressions of EndoG and hTERT splice variants have been found to be correlated in several colon cancer cell lines." (PMID 35974340, 2022). "Up-regulation of EndoG in a colon cancer cell line has led to downregulation of the active full-length hTERT variant and up-regulation of non-active alternatively spliced variants." (PMID 35974340, 2022). "Besides this, LL-37 also increases the nuclear translocation of apoptosis-inducing-factor (AIF) and endonuclease G (EndoG) in colon cancer cells to induce apoptosis." (PMID 36559179, 2022). "Among them, LL37 and FK-16 induced caspase-independent apoptosis of colon cancer cells by inducing the nuclear translocation of AIF and EndoG through the upregulation of Bax and Bak and the downregulation of Bcl-2." (PMID 38069041, 2023). "Although FK-16, a shorter fragment of LL-37, induced autophagy in colon cancer cells, it was also proved to augment AIF−/EndoG-dependent apoptosis in colon cancer cells when autophagy was inhibited." (PMID 35935871, 2022). "Caspase-independent apoptosis of colon cancer cells is mediated by apoptosis inducing factor (AIF) and endonuclease G (EndoG), involved in DNA degradation." (PMID 26395996, 2016). "Reciprocally, abolition of AIF/EndoG-dependent apoptosis by AIF- or EndoG-siRNA enhanced Atg5 and Atg7 expression induced by FK-16, indicating that inhibition of AIF/EndoG-dependent apoptosis magnified the autophagic signal in FK-16-treated colon cancer cells." (PMID 23700428, 2013). "Moreover, Ren and colleagues found that the human microbial preventive peptides (LL-37) treatment of human colon cancer cell lines led to the nuclear translocation of apoptosis-inducing factor (AIF) and endonuclease G (EndoG), key mediators of caspase-independent apoptosis." (PMID 40867294, 2025).
breast carcinoma (5 papers, 2015 to 2024). "TRPA1 activation in glioma and breast cancer cells induces mitochondrial damage and apoptosis via cytochrome-c, the activation of caspase 3 and 9, and the release of apoptosis-inducing factors and endonuclease G." (PMID 38612571, 2024). "In human breast cancer cells, AITC induced mitochondrial-mediated apoptosis via cytochrome-c and release of apoptosis inducing factor and endonuclease G, as well as the activation of caspase-9 and caspase-3." (PMID 35163843, 2022).
Cerebral ischemia (4 papers, 2009 to 2025). Restriction of arterial blood supply to the brain associated with insufficient oxygenation to support the metabolic requirements of the tissue. "This is consistent with a previous report in a mouse model of brain ischemia, in which EndoG translocation was observed 4 h after transient focal cerebral ischemia." (PMID 19737385, 2009). "Although ENDOD1 has not been directly associated with stroke or ischemia, the established involvement of other endonuclease-related proteins (e.g., endonuclease VIII-like 1 and endonuclease G) in ischemic injury suggests a potential, yet unexplored, relevance in cerebral ischemia." (PMID 41342963, 2025). "We previously observed the involvement of EndoG in BNIP3-induced cell death in models of hypoxia and cerebral ischemia." (PMID 25436615, 2014).
colorectal cancer (4 papers, 2016 to 2024). A primary or metastatic malignant neoplasm that affects the colon or rectum. "This strategy can also be considered for the treatment of cancers with high EndoG expression such as gastric or colorectal cancers." (PMID 36734593, 2023). "The proposed mechanism in this study is likely to at least partly contribute to tumorigenesis in gastric and colorectal cancer through the upregulation of EndoG." (PMID 36734593, 2023). "Upregulation of EndoG has been shown in gastric and colorectal cancer patient tissues via immunohistochemistry." (PMID 36734593, 2023).
ischemia (4 papers, 2009 to 2025). A hypoperfusion of the BLOOD through an organ or tissue caused by a PATHOLOGIC CONSTRICTION or obstruction of its BLOOD VESSELS, or an absence of BLOOD CIRCULATION. "Previous research by Bahi and coworkers has demonstrated that the release of EndoG together with AIF from mitochondria to cytosol in rat postnatal differentiated cardiomyocytes is induced by experimental ischemia and causes DNA degradation in cardiomyocytes thereafter." (PMID 28272306, 2017). "TUNEL-positive DNA damage, which depends on caspase activity in other cells, is caspase-independent in ischemic cardiomyocytes and ischemia-induced DNA high and low molecular weight fragmentation is blocked by repressing EndoG expression." (PMID 21437288, 2011). "We have recently reported that EndoG is important for DNA degradation in cardiomyocytes, where the caspase-dependent pathway is repressed during differentiation and is not re-expressed during experimental ischemia." (PMID 21437288, 2011). "Both EndoG and Bnip3, but not Nix, were essential for inducing TUNEL-positive DNA fragmentation in experimental ischemia, which did not involve caspase activity." (PMID 21437288, 2011).
endometrial cancer (3 papers, 2021 to 2023). Primary or metastatic malignant neoplasm involving the endometrium (mucous membrane that lines the endometrial cavity). "The results obtained from the analysis of ENDOG expression in the endometrial cancer databases showed a direct association of ENDOG expression and PTEN gene mutations and less aggressive histological subtypes." (PMID 34359707, 2021). "Accordingly, ENDOG expression was found to be associated with a more favorable prognosis in endometrial cancer in TCGA data only for overall survival (p = 0.0062), but not for disease-free survival." (PMID 34359707, 2021). "As we had observed that ENDOG expression correlated with mutations of the PTEN gene in endometrial cancer, we considered the relationship of ENDOG expression and PTEN status in CLL." (PMID 34359707, 2021). "We silenced ENDOG expression in Ishikawa 3-H-12 (IK) cells, a tumor cell model of endometrial carcinoma, which is PTEN-deficient and has high p-Ser473-AKT expression." (PMID 34359707, 2021). "Finally, in silico data suggest that ENDOG expression associates with PTEN status in endometrial cancer and that its prognostic value in some CLL subtypes is also dependent on PTEN expression levels." (PMID 34359707, 2021). "Moreover, ENDOG expression associates with PTEN/p-AKT status in endometrial cancer and also has prognostic value in a tumor cell model with AKT hyperactivation, such CLL, but this depends on PTEN expression levels." (PMID 34359707, 2021). "In particular, in endometrial cancer cells, ENDOG silencing hampers proliferation of IK cells, which lack PTEN and have high levels of p-AKT." (PMID 34359707, 2021). "Contrary to endometrial carcinoma, ENDOG median expression was slightly lower in the indolent CLL subtype (M-CLL) compared to the aggressive one (U-CLL) (p = 0.014)." (PMID 34359707, 2021). "Notably, ENDOG silencing inhibited cell growth of endometrial cancer, thyroid carcinoma, and glioblastoma." (PMID 34992654, 2021). "Then, we analyzed the expression of ENDOG and several members of the PI3K/AKT pathway, both in several endometrial carcinoma cell lines and primary tumor databases, to investigate a possible association among them." (PMID 34359707, 2021).
gastric cancer (3 papers, 2016 to 2021). A primary or metastatic malignant neoplasm involving the stomach. "Moreover, ENDOG overexpression in colorectal and gastric cancer cells associated with tumour development." (PMID 34366863, 2021).
glioma (3 papers, 2012 to 2024). A benign or malignant brain and spinal cord tumor that arises from glial cells (astrocytes, oligodendrocytes, ependymal cells). "In C6 glioma cells, Cas IIgly also induces apoptosis by a caspase-independent mechanism, mediated by apoptosis induction factor (AIF) and endonuclease G." (PMID 22540380, 2012).
Obesity (3 papers, 2023 to 2025). Accumulation of substantial excess body fat. "In this paper, we provide evidence that decreased levels of mitochondrial endonuclease G contribute to obesity-independent MASLD in male mice." (PMID 39752519, 2025). "Because SIRT6 regulates ENDOG/SOD2, it helps reduce myocardial oxidative stress caused by obesity resulting from a high-fat diet." (PMID 41567643, 2025). "EndoG expression is reduced in MASLD liver, and EndoG deficiency causes MASLD in an obesity-independent manner but only in males." (PMID 39752519, 2025). "Although its role in the mitochondria still remains an open question, ENDOG has been found to play a major role in the pathogenesis of mitochondria-related diseases such as cardiac hypertrophy, Parkinson’s disease and obesity." (PMID 37834200, 2023).
cardiac hypertrophy (2 papers, 2021 to 2023). "In vivo and in vitro experimental data also demonstrated that endonuclease G (Endog) loss-of-function may serve as a novel determinant of decompensated cardiac hypertrophy and impaired cardiac function." (PMID 35118147, 2021).
cardiac ischemia (2 papers, 2017 to 2022). "As shown in our data, increased apoptosis was observed in ischemic cardiomyocytes compared with control; suppressed AIF or EndoG expression correlates with a significant reduction of DNA damage to nearly the same level as cardiomyocytes only treated with AKT2 inhibitor during cardiac ischemia." (PMID 28272306, 2017). "Our results show that AKT2 inhibition induces a unique mitochondrial-dependent DNA degradation pathway by activating nucleus translocation of AIF and EndoG during cardiac ischemia, suggesting a new function and mechanism of AKT2 in regulating cardiomyocyte survival." (PMID 28272306, 2017). "However, non-caspase-dependent apoptotic pathways can also be activated under DOX or cardiac IR condition, as evidenced by AIF translocation to the nuclei in H9c2 cardiomyoblasts treated with DOX and intracytosolic translocation of AIF and endonuclease G during cardiac ischemia." (PMID 35747748, 2022).
glioblastoma (2 papers, 2021). The most malignant astrocytic tumor (WHO grade IV). "For the two GBM cell lines studied, ENDOG gene silencing caused a reduction in the proliferation of the U251 glioblastoma cell line, which showed cell cycle arrest in the S phase." (PMID 34359707, 2021). "Finally, we considered the study of ENDOG silencing in U87 and U251 glioblastoma cell lines characterized, among other traits, by the absence of PTEN expression and in which PTEN overexpression has been shown to sensitize to cell death inducers." (PMID 34359707, 2021). "Furthermore, ENDOG silencing reduced proliferation of follicular thyroid carcinoma and glioblastoma cell lines with high p-AKT expression." (PMID 34359707, 2021). "First, we measured expressions of ENDOG, p-AKT, AKT and PTEN in FTC-133 follicular thyroid carcinoma cells, CAL-62 thyroid anaplastic carcinoma, HT-29 colorectal adenocarcinoma cells and U87 and U251 glioblastoma multiforme (GBM)-derived cancer cell lines." (PMID 34359707, 2021).
Hepatic steatosis (2 papers, 2023 to 2025). Steatosis is a term used to denote lipid accumulation within hepatocytes. "H&E staining of liver sections showed that loss of ENDOG ameliorated HFD-induced hepatic steatosis." (PMID 37794041, 2023).
Hypertension (2 papers, 2021). The presence of chronic increased pressure in the systemic arterial system. "In this present study, exercise training was found to reduce hypertension-induced EndoG/AIF-related caspase-independent apoptotic pathways in the cerebral cortex which was evidenced by reduced expression levels of EndoG and AIF." (PMID 34432648, 2021).
lung carcinoma (2 papers, 2013 to 2021). "Since 83% of HeLa cells but only 9% of A549 cells revealed increased caspase-3 activity following siRNA-LAMR1 treatment, we further suggest that apoptosis in lung cancer cells may occur predominantly via caspase-3 independent mechanisms such as EndoG and/or AIF mediated processes." (PMID 23472084, 2013).
Mitochondrial myopathy (2 papers, 2022 to 2024). "Here, we report biallelic novel ENDOG variants, identified by NGS in a patient with progressive external ophthalmoplegia (PEO), mitochondrial myopathy and multiple mtDNA deletions in the muscle." (PMID 35326425, 2022). "Here, we report biallelic ENDOG variants identified by NGS in a patient with progressive external ophthalmoplegia, mitochondrial myopathy and multiple mtDNA deletions in muscle." (PMID 35326425, 2022).
multiple myeloma (2 papers, 2018 to 2025). "Overall, the lactoferrin-derived chimera induces caspase-independent programmed cell death in multiple myeloma cell lines by increasing the nuclear translocation of apoptosis-inducing factor/endonuclease G. Therefore, it has potential for multiple myeloma cancer therapies." (PMID 39937008, 2025).
oral squamous cell carcinoma (2 papers, 2014 to 2016). "Safingol, L- threo-dihydrosphingosine, induces cell death in human oral squamous cell carcinoma (SCC) cells through an endonuclease G (endoG) -mediated pathway." (PMID 27658240, 2016). "Safingol, a L-threo-dihydrosphingosine, induced the nuclear translocation of a mitochondrial apoptogenic mediator—endonuclease G (endo G)—and apoptosis of human oral squamous cell carcinoma (SCC) cells." (PMID 24549171, 2014). "We showed that safingol released the apoptogenic factor, endonuclease G (endoG), from mitochondria, which translocated into the nucleus, and this was followed by the apoptosis of human oral squamous cell carcinoma (SCC) cells at concentrations of 25 μM and 50 μM." (PMID 27658240, 2016).
thyroid cancer (2 papers, 2021). "Regarding the thyroid cancer cell models, the FTC-133 cell line, which has a hemizygous deletion of the PTEN gene and high p-AKT abundance, is sensitive to ENDOG silencing, whereas the CAL-62 cell line, which expresses high PTEN levels, is not." (PMID 34359707, 2021).
acute monocytic leukemia (1 paper, 2018). Acute monoblastic leukemia (AML-M5), is one of the most common subtypes of acute myeloid leukemia (AML) that is either comprised of more than 80% of monoblasts (AML-M5a) or 30-80% monoblasts with (pro)monocytic differentiation (AML-M5b). "Taken together, our findings suggest that cell cycle arrest, endonuclease G-mediated apoptosis, and autophagy inhibition contribute to the anti-cancerous effect of WSPIS on human acute monocytic leukemia cells." (PMID 29382173, 2018).
B-cell neoplasm (1 paper, 2021). A group of heterogeneous lymphoid tumors generally expressing one or more B-cell antigens or representing malignant transformations of B-lymphocytes. "In this context we decided to explore the clinical impact of ENDOG in CLL as a model of B-cell neoplasm in which the PI3K-AKT axis is constitutively activated and required for cell survival and proliferation." (PMID 34359707, 2021).
breast tumor (1 paper, 2023). "In order to determine the significance of Endo G in isolated mitochondria, experiments were conducted on breast tumor cells in which ENDOG gene was knocked down, and the CRISPR‐untreated MDA‐MB‐453 was used as recipient cells." (PMID 37206227, 2023).
cervical cancer (1 paper, 2022). A primary or metastatic malignant neoplasm involving the cervix. "Merge of MitoTracker with tagged Endonuclease G revealed localization of Endonuclease G in mitochondria in HeLa (human cervical cancer), HEK 293T (human embryonic kidney epithelial) and MEF (mouse embryonic fibroblast) cell lines." (PMID 36394256, 2022).